MTRF1 (mitochondrial translation release factor 1)
Description:
Mitochondrial peptide chain release factor that directs the termination of translation in response to the peptide chain non-canonical stop codons AGG and AGA. Non-canonical termination codons AGG and AGA are found at the end of MT-CO1/COX1 and MT-ND6/ND6 open reading frames, respectively. Recognizes non-canonical stop codons via a network of interactions between the codon, MTRF1 and the ribosomal RNA (rRNA): in contrast to other translation release factors, which identify the codon in the A-site via direct interactions of amino acid side chains with the bases, MTRF1 repositions the first 2 bases of the stop codon to use an intricate network of interactions that includes residues of the release factor, the rRNA of the small ribosomal subunit, as well as neighboring bases of the mRNA.
Synonyms: RF1; MTTRF1; MGC47721; MRF1
Tractability: Small molecule: a structure with a bound ligand is known. PROTAC: ubiquitination databases record sites on it; its protein half-life has been measured.
Gene: Protein-coding gene on chromosome 13 (41,216,145 to 41,263,775, reverse strand). Ensembl gene ENSG00000120662.
Subcellular location: Mitochondrion
Pathways (Reactome):
Metabolism of proteins: Mitochondrial translation termination
Gene Ontology:
Molecular function: translation release factor activity, codon specific; translation release factor activity
Biological process: mitochondrial translational termination; translational termination
Cellular component: mitochondrion; mitochondrial matrix
Genetic constraint (gnomAD): Loss-of-function variants: 40 observed, 51.18 expected, observed/expected ratio (o/e) 0.78, 90% interval 0.61 to 1.02. The upper end of that interval is the gene's LOEUF score, 1.02, which puts it in group 4 of 6, group 1 being the genes least tolerant of losing a copy. Missense variants: 391 observed, 491.22 expected, observed/expected ratio (o/e) 0.8, 90% interval 0.73 to 0.87. Synonymous variants: 140 observed, 169.47 expected, observed/expected ratio (o/e) 0.83, 90% interval 0.72 to 0.95.
Homologues: Orthologues: chimpanzee MTRF1 (100% identical), macaque MTRF1 (97% identical), rabbit MTRF1 (87% identical), dog MTRF1 (87% identical), pig MTRF1 (87% identical), guinea pig MTRF1 (86% identical), mouse Mtrf1 (82% identical), rat Mtrf1 (74% identical), Drosophila melanogaster mRF1 (32% identical), zebrafish mtrf1 (31% identical). Paralogues in human: MTRF1L (38% identical), MRPL58 (9% identical).
Diseases named in the same sentence as MTRF1 in open-access papers:
MTRF1 is named in the same sentence as 1 disease in open-access papers, as found by Europe PMC text mining. Sharing a sentence is not in itself a finding about the gene and the disease.
MTRF1 shares sentences with these, for which no sentence is quoted: schizophrenia (1 paper).